CPA3 (carboxypeptidase A3)
Diseases named in the same sentence as CPA3 in open-access papers (continued):
Sharing a sentence is not in itself a finding about the gene and the disease.
melanoma (7 papers, 2013 to 2024). A malignant, usually aggressive tumor composed of atypical, neoplastic melanocytes. "Here we addressed this possibility by evaluating mice deficient in chymase (Mcpt4−/−), tryptase (Mcpt6−/−) or CPA3 (Cpa3−/−) in a model of melanoma colonization of the lung." (PMID 28212574, 2017). "As a next approach for dissecting the mechanism underlying the protective role of Mcpt4/Mcpt6/Cpa3 in melanoma colonization, we assessed the levels of various cytokines and chemokines in serum of WT vs. multiple KO mice using an antibody-based filter array." (PMID 28212574, 2017). "This was supported by higher expression of melanoma-specific genes in lungs of Mcpt4/Mcpt6/CPA3-deficient vs. wildtype mice." (PMID 28212574, 2017). "Moreover, our data suggest that the enhanced melanoma colonization seen in Mcpt4/Mcpt6/Cpa3-deficient animals is associated with a defective CXCL16/CD1d/iNKT cell axis." (PMID 28212574, 2017). "Next we considered the possibility that the altered melanoma colonization in Mcpt4/Mcpt6/Cpa3-deficient animals might be reflected by effects on leukocyte recruitment into the lungs." (PMID 28212574, 2017). "Hence, the high melanoma burden of Mcpt4/Mcpt6/Cpa3-deficient animals is accompanied by low expression of CD1d, introducing the possibility that CD1d might have a role in regulating melanoma colonization of the lung." (PMID 28212574, 2017). "Conversely, evidence is available for an anti-tumorigenic role of MCs in melanoma showing that MC proteases including tryptase, chymase, and carboxypeptidase A3 promote cytotoxic T and NKT cells." (PMID 35669782, 2022). "Experimental studies in genetically-altered mice indicate that the combined actions of chymase, tryptase and CPA3 protect against the formation of lung metastasis of melanoma." (PMID 31500217, 2019). "The absence of the MC protease system will accordingly lead to an elevation of factors with tumor-promoting activity; however, the identities of the in vivo substrates for Mcpt4/Mcpt6/Cpa3 during the course of melanoma progression remain to be revealed." (PMID 28212574, 2017). "As an alternative scenario explaining for the effect of NDST2 on melanoma, it is noteworthy that heparin is crucial for promoting the storage of MC proteases, including Mcpt4, Mcpt5, Mcpt6 and Cpa3." (PMID 28212574, 2017). "As regards the molecular mechanism by which the mast cell proteases affect melanoma dissemination, our findings reveal that the absence of Mcpt4/Mcpt6/Cpa3 is associated with a decrease in ADAM17 expression." (PMID 28212574, 2017). "Hence, these findings reinforce that the combined action of Mcpt4, Mcpt5, Mcpt6 and Cpa3 protects against melanoma colonization of lungs." (PMID 28212574, 2017). "We also noted that the absence of Mcpt4/Mcpt6/CPA3 was associated with alterations in the expression a range of other genes of potential impact on the melanoma colonization processes: HGF, MMP2, FGF, CXCL2." (PMID 28212574, 2017). "The proteases assessed in this study, i.e. Mcpt4, Mcpt6 and CPA3 (and indirectly Mcpt5), are all expressed by MCs of the connective tissue subtype (CTMCs), and our findings thus indicate the proteases expressed by this subclass of MCs influence melanoma colonization." (PMID 28212574, 2017). "Interestingly, single defects in any of the MC proteases were insufficient to cause increased melanoma progression whereas the simultaneous depletion of Mcpt4/Mcpt6/Cpa3 at the gene level (combined with post-translational defects in Mcpt5 storage) led to a significant increase in melanoma burden." (PMID 28212574, 2017). "When assessing the Mcpt4/Mcpt6/Cpa3 multiple knockout (KO) strain in our model, we noted that the melanoma colonization of lung tissue was markedly higher than in WT mice, suggesting that the combined action of Mcpt4, Mcpt6, Cpa3 and Mcpt5 is protective against melanoma dissemination to the lung." (PMID 28212574, 2017).
melanoma (continued). "It is possible that the peptide sequence recognized by serum antibodies of the melanoma patient on the CPA3 protein is the mimic of a conformational or carbohydrate epitope on the other human, viral or bacterial protein, which may represent the unknown real target of the humoral immune response." (PMID 23826227, 2013). "In a previous study we approached this issue and showed that the combined absence of tryptase, chymase, and CPA3 can lead to increased tumor progression in a melanoma model." (PMID 31506436, 2019). "The data above suggest that the simultaneous absence of Mcpt4/Mcpt6/Cpa3 results in increased melanoma colonization as manifested by the appearance of tumor nodules in lungs taken two weeks after melanoma cell administration." (PMID 28212574, 2017). "We show that melanoma colonization of the lungs is enhanced in animals with simultaneous absence of chymase, tryptase and CPA3, suggesting a protective role of the MC-restricted proteases." (PMID 28212574, 2017). "This suggests that the individual absence of Mcpt4, Mcpt6 or CPA3, respectively, does not affect the outcome in this model of melanoma colonization." (PMID 28212574, 2017). "Although the individual absence of Mcpt4, Mcpt6 or CPA3 did not affect melanoma dissemination to the lung, we considered the possibility that the combined action of these proteases can have an impact on melanoma colonization." (PMID 28212574, 2017). "Here we addressed this issue by assessing mice lacking either the chymase Mcpt4, the tryptase Mcpt6 or carboxypeptidase A3 (Cpa3), as well as mice simultaneously lacking all three proteases, in a model of melanoma dissemination from blood to the lung." (PMID 28212574, 2017). "When we analyzed the reactivity of the melanoma serum sample against the next ranked highest after the CPA3 protein, the serum antibody did not detect the corresponding band on the western blot." (PMID 23826227, 2013). "Possibly, chymase and/or CPA3 could have in vivo anti-tumor effects that are not due to direct interaction with melanoma cells, for example by affecting the tumor microenvironment." (PMID 31506436, 2019). "Next, we asked whether the absence of Mcpt4/Mcpt6/Cpa3 affects melanoma colonization at the early stages, i.e. before the appearance of visible tumor nodules." (PMID 28212574, 2017). "Our findings thus suggest that the iNKT cell population may be impaired in mice lacking Mcpt4/Mcpt6/Cpa3, which could lead to impaired protection against melanoma dissemination." (PMID 28212574, 2017). "In order to approach the mechanism by which the combined absence of Mcpt4/Mcpt6/Cpa3 could affect melanoma colonization, we first assessed the expression of various genes known to have an impact on malignant progression/dissemination." (PMID 28212574, 2017).
colon cancer (6 papers, 2013 to 2023). "Interestingly, CPA3 has recently been highlighted in multiple gene signature studies where CPA3 expression has been linked to eosinophilic esophagitis, colon cancer, and eosinophilic type 2 asthma." (PMID 33546258, 2021). "CPA3 belongs to carboxypeptidase family of zinc metalloproteases released by mast cells and has been demonstrated to be involved in endogenous proteins degradation as well as colon cancer prognosis." (PMID 36925638, 2023). "In parallel studies for downregulated genes, we were able to identify seven genes with mutations in colon cancer (DPP10, PCSK2, ADAM33, RELN, CAPN13, ADAMTS1 and ADAMTS15), and five genes with mutations in breast carcinomas (MASP3, ABHD12B, TLL1, CPA3 and DPP6)." (PMID 24243807, 2013). "CPA3 was reported as a prognostic biomarker in colon cancer, but its role has not been fully investigated in cancers." (PMID 37583701, 2023).
lung fibrosis (5 papers, 2016 to 2024). "Moreover, increased levels of CPA3 have been reported in ILDs, such as idiopathic pulmonary fibrosis (IPF)." (PMID 39596322, 2024). "We found that mRNAs encoding LOYBOY, DEEZOY, and SNEYSPORBY were upregulated, and those encoding CPA3, FCER1A, and CCR5 were downregulated; these mRNAs may be involved in silica-induced lung fibrosis." (PMID 30756084, 2019). "Moreover, the upregulation of the IFN signaling leads to increased bradykinin signaling (via ACE2 upregulation), that together with higher levels of CPA3 and ADAMTS1 can lead to lung fibrosis." (PMID 33479353, 2021).
anaphylaxis (4 papers, 2016 to 2021). An acute hypersensitivity reaction that occurs from exposure to an allergen. "Another study also used a sandwich-based EIA to measure levels of carboxypeptidase A3 in cases of suspected anaphylaxis (n = 181), systemic mastocytosis, and control groups of healthy blood donors (n = 209), or individuals with bronchial asthma (n = 15)." (PMID 31024519, 2019). "The in vitro diagnosis of anaphylaxis includes serial measurement of the mediators released during an anaphylactic reaction, namely, tryptase, histamine, chymase, carboxypeptidase A3, platelet-activating factor, and other products from mastocytes." (PMID 29238519, 2017). "There is growing evidence to support the investigation of other biomarkers, such as chymase, carboxypeptidase A3, dipeptidyl peptidase I (DPPI), basogranulin, CCL-2, and platelet activating factor (PAF) in the diagnosis of anaphylaxis." (PMID 31024519, 2019). "There has been an interest in the detection of newer biomarkers in anaphylaxis including platelet activation factor (PAF), chymase, carboxypeptidase A3, dipeptidyl peptidase I (DPPI), basogranulin, and CCL-2." (PMID 31024519, 2019). "Carboxypeptidase A3 levels were elevated (>14 ng/mL) in serum from patients with a clinical diagnosis of anaphylaxis, but not in healthy controls or those with atopy." (PMID 34575019, 2021). "Serum CPA3 levels have also been reported to be elevated in those with a clinical diagnosis of anaphylaxis but not in the serum of adult healthy blood donors or individuals with a diagnosis of asthma of another IgE-mediated allergic disease." (PMID 26904159, 2016). "Furthermore, carboxypeptidase A3 was also elevated in 70% of the 110 cases of suspected anaphylaxis cases that were MCT negative." (PMID 31024519, 2019). "The serum levels of tryptase and of CPA3 after anaphylaxis do not necessarily correlate." (PMID 26904159, 2016).
chronic obstructive pulmonary disease (4 papers, 2022 to 2024). A chronic and progressive lung disorder characterized by the loss of elasticity of the bronchial tree and the air sacs, destruction of the air sacs wall, thickening of the bronchial wall, and mucous accumulation in the bronchial tree. "In addition, increased CPA3 expression has been associated with blood and airway eosinophilia in patients with chronic obstructive pulmonary disease." (PMID 38578780, 2024). "In this context it is worth noting that CPA3 counts were high and CPA3 expression has been shown to correlate to decreased lung function in patients with severe chronic obstructive pulmonary disease (COPD) and idiopathic lung fibrosis (IPF)." (PMID 37063885, 2023). "Although Cpa3 and mMCP-5 deficiency in mice did not affect symptoms in acute asthma models in the present study, we cannot exclude a role for CPA3 in human chronic airway diseases such as asthma and chronic obstructive pulmonary disease (COPD)." (PMID 38578780, 2024).
Obesity (4 papers, 2020 to 2025). Accumulation of substantial excess body fat. "Promoter hypomethylation is typically associated with increased transcriptional activity of the corresponding gene, which is consistent with the observed CPA3 expression levels in children with obesity." (PMID 40869388, 2025). "The most significant findings included hypermethylation of CpG cg11024682, located within the body of the SREBF1 gene, and hypomethylation of cg13424229, situated in a GATA binding factor 1 cluster within the promoter region of CPA3, in patients with early-onset obesity." (PMID 40869388, 2025). "Therefore, our findings suggest that elevated NMUR1 and CPA3 expression is associated with obesity but not age." (PMID 36232539, 2022). "In underexpressed genes, obesity did not affect PI3, CHI3L1, and IL-8 and significantly reduced CPA3 expression." (PMID 37445432, 2023).
allergy (3 papers, 2019 to 2025). An allergy is an immune response or reaction to substances that are usually not harmful. "The authors found that carboxypeptidase A3 levels were significantly greater in the serum or plasma collected within 8 h of an onset of allergic reaction, compared to the control cohort." (PMID 31024519, 2019).
emphysema (3 papers, 2021 to 2023). "A notable finding in female E-dominant COPD is the expression of mast cell associated genes like tryptase B2, tryptase AB1 and the peptidase CPA3, suggesting a role for mast cells in the pathophysiology of emphysema dominant COPD in females." (PMID 34145303, 2021). "Interestingly, in another COPD study, increased sputum CPA3 was particularly high in female patients with HRCT-defined emphysema." (PMID 35983043, 2022). "For females the top differential emphysema-restricted genes are the mast cell specific genes TPSB2, TPSAB1 and CPA3." (PMID 34145303, 2021). "Regarding the upregulated DEGs in COPD, CD109, B cell linker (BLNK), interleukin-1 receptor type 1 (IL1R1), CD1A, and carboxypeptidase A3 (CPA3) are related to T-helper cell type 2 (Th2) inflammation, but not to emphysema formation." (PMID 38203236, 2023). "CPA3 upregulation could be reflected by airway inflammation and not by emphysema formation." (PMID 38203236, 2023).
rheumatoid arthritis (3 papers, 2020 to 2024). A chronic, systemic autoimmune disorder characterized by inflammation in the synovial membranes and articular surfaces. "Elevated adenosine deaminase has been observed in patients with rheumatoid arthritis, and the enzyme can be cleaved by mast cell-released CPA3 to produce PAMP-12." (PMID 39144634, 2024). "Several other TG-affected genes showed weaker associations with atherosclerosis-related outcomes (ABCG1, AC004791.2, CPA3, CYP11A1, SLC12A3) or rheumatoid arthritis (GATA2, SMPDL3A) but were no longer statistically significant after correction for multiple testing (PFDR > 0.05)." (PMID 36725846, 2023).
allergic asthma (2 papers, 2024 to 2025). A asthma with a basis in a pathological type I hypersensitivity reaction. "In order to investigate the role of CPA3 and mMCP-5 in HDM-induced allergic asthma, WT and Cpa3-/- mice were given HDM intranasally (i.n.)twice weekly for three weeks." (PMID 38578780, 2024).
Arthritis (2 papers, 2012 to 2016). Inflammation of a joint. "Induction of arthritis by K/BxN serum transfer in, for example, Cpa3-cre mice induced clinical arthritis, which was comparable to mast cell-competent mice." (PMID 27296719, 2016).
Azoospermia (2 papers, 2024). Absence of any measurable level of sperm,whereby spermatozoa cannot be observed even after centrifugation of the semen pellet. "The cytological and histotopographic features of testicular CPA3+ MCs were examined in a study involving 34 men with azoospermia." (PMID 38786055, 2024). "We can assume that testicular MCs contain high levels of CPA3, the content of which changes dynamically depending on the conditions of the tissue microenvironment of the testicle, including the formation of azoospermia." (PMID 38786055, 2024). "As revealed, in cases with non-obstructive azoospermia, a higher content of CPA3+ MCs in the TIT and migration to the microvasculature and peritubular tissue of seminiferous tubules were observed when compared with cases with obstructive azoospermia." (PMID 38786055, 2024).
breast carcinoma (2 papers, 2013 to 2023). "For example, the expression level of CPA3 elevated after chemotherapy in treating breast cancer tissues." (PMID 37684436, 2023).
eosinophilic esophagitis (2 papers, 2021 to 2025). Eosinophilic esophagitis (EoE) is a chronic, allergic disease of the esophagus characterized clinically by symptoms of esophageal dysfunction (including vomiting, dysphagia, feeding disorders, food impaction and abdominal pain) which persist after treatment with proton pump inhibitors (PPIs). "MCTs preferentially expand within the epithelium during T2 inflammation, where they further express CPA3 in T2-high asthma, CRSwNP, and eosinophilic esophagitis (EoE)." (PMID 39744949, 2025). "However, this interdependence and co-localization seems not to be strict, since subsets of MCs containing CPA3 but lacking chymase have been observed in asthmatic airways, allergic rhinitis and eosinophilic esophagitis." (PMID 33546258, 2021).
fibrosis (2 papers, 2022 to 2024). the formation of excess fibrous connective tissue in an organ or tissue in a reparative or reactive process. "As expected, our IPF sections were characterized by classical IPF histopathological features like parenchymal fibrosis, accumulation of distal lung myofibroblasts and honeycombing and that these changes were accompanied with a combined striking increase in both MC density and CPA3 expression." (PMID 35983043, 2022).
mastocytosis (2 papers, 2019 to 2021). A clonal myeloproliferative neoplasm characterized by the proliferation and accumulation of neoplastic mast cells in one or multiple organs or organ systems. "Also, that mastocytosis is a growing conjoint of diseases that gives rise, among others, to massive extracellular release of carboxypeptidase A3 from degranulated mastocytes, constituting a potential therapeutic target for carboxypeptidase inhibitors." (PMID 31470614, 2019).
Achalasia (1 paper, 2022). A disorder of esophageal motility characterized by the inability of the lower esophageal sphincter to relax during swallowing and by inadequate or lacking peristalsis in the lower half of the body of the esophagus. "Among the inflammation-related genes, our study indicates significant up-regulation of the mast cell peptidase CPA3 in the mucosa of achalasia patients." (PMID 36450816, 2022). "Although our findings suggest an association between CPA3+ mast cells and IL-33 in the esophageal mucosa of achalasia, the lack of significant increase of CPA3 in proximal esophagus also implies a role for IL-33 on other immune cell types in achalasia." (PMID 36450816, 2022). "CPA3 mRNA expression levels were significantly up-regulated in the distal mucosa of achalasia subjects compared to controls, but not in the proximal esophagus." (PMID 36450816, 2022).
age (1 paper, 2024). A temporal measurement of the time period elapsed since an identifiable point in the life cycle of an organism. "Elevated CPA3 expression in age-related MMVD suggests heightened mast-cell-driven immune responses, potentially intensifying the inflammatory milieu and accelerating degenerative alterations." (PMID 38753730, 2024).
autoimmune disease (1 paper, 2024). A disorder resulting from loss of function or tissue destruction of an organ or multiple organs, arising from humoral or cellular immune responses of the individual to their own tissue constituents. "Genes CPA3 and GATA2 expression were positively associated with levels of leptin, suggesting a genetic overlap between AN, autoimmune disease, and metabolic function." (PMID 39462405, 2024).
Chlamydia infection (1 paper, 2023). "We investigated the role of mast cells in a reproductive tract Chlamydia infection model using Cpa3-Cre; Mcl-1fl/fl ‘Hello Kitty’ (HK) mice." (PMID 37138882, 2023).
colitis (1 paper, 2020). Inflammation of the colon. "Moreover, oral cinnamon extract treatment caused a downregulation of tryptase and carboxypeptidase A3 (MC-CPA) expression and reduced expression of mast cell proteases (MC-CPA, MCP-1 and MCP-4) and pro-inflammatory mediators (CXCL8, CCL2, CCL3 and CCL4) during colitis in IL-10 knockout mice." (PMID 32962285, 2020).